IL4R (interleukin 4 receptor)
Diseases named in the same sentence as IL4R in open-access papers (continued):
Sharing a sentence is not in itself a finding about the gene and the disease.
Anxiety (4 papers, 2022 to 2025). Intense feelings of nervousness, tension, or panic often arise in response to interpersonal stresses. "We here demonstrate that IL-4 is present within the brain parenchyma and that IL-4Rα deficiency leads to reduced anxiety levels with impaired fear stimulus learning and exploratory drive while general learning is not affected." (PMID 35587822, 2022). "In fact, the deficiency of IL-4Rα resulted in increased network activity in vivo, accompanied by altered exploration and anxiety-related learning behavior; general learning and memory was unchanged." (PMID 35587822, 2022). "The modulation of neuronal IL-4R signaling alters the neuronal transcriptome, impacts synaptic transmission, and causes anxiety-related behavior." (PMID 35587822, 2022). "Thus, neuronal IL-4Rα deficiency reduced the inhibition of excitatory neurons, resulting in increased exploratory behavior and locomotion, decreased anxiety levels, and impairments in fear learning." (PMID 40551129, 2025). "To examine how IL-4R deficiency in neuronal network activity translates to behavior, we used a battery of tests for anxiety (light–dark box, elevated plus maze) as well as general learning and memory (novel object interaction, Y-maze, Morris water maze, and fear conditioning)." (PMID 35587822, 2022). "This study found that IL-4Rα inhibition reduced anxiety-like behaviour, while Diminazine treatment increased anxiety-like behaviour in trypanosomiasis." (PMID 40977748, 2025). "Our data therefore points to some role of IL-4Rα as one of the key regulators of gene expression changes recruited in the functional activation of neural networks that mediate locomotor, anxiety and reference memory to trypanosome infection effects." (PMID 40977748, 2025). "Research indicates that blocking IL-4Rα prevents the anxiolytic effects of certain treatments, highlighting the importance of IL-4 signalling in regulating anxiety." (PMID 40977748, 2025). "The present study investigated the influence of Trypanosomiasis on anxiety-like behaviour in the elevated plus maze in WT and IL-4Rα┴ mice treated with Iloprost." (PMID 40977748, 2025). "In the context of trypanosome-induced neuroinflammation, inhibiting IL-4Rα could potentially worsen anxiety-related behaviours by amplifying inflammatory responses within the CNS." (PMID 40977748, 2025). "Interestingly, IL-4Rα inhibition appeared to reduce anxiety-like behaviours in infected mice, while Iloprost treatment had an anxiolytic effect." (PMID 40977748, 2025). "Pan-neuronal IL-4Rα deficiency leads to abnormal network activity, hyperlocomotion, and higher exploratory behavior, as well as anxiety-related learning deficits, but does not contribute to general learning or memory." (PMID 35587822, 2022). "Moreover, IL-4Rα inhibition was associated with downregulation of anti-inflammatory cytokines, upregulation of TNF-α and nitric oxide, and altered BDNF expression, collectively contributing to cognitive dysfunction and exacerbated neuroinflammation and anxiety-like behaviours." (PMID 40977748, 2025). "Neuronal IL-4Rα, therefore, plays a distinct modulatory role in cognition, with no obvious effects on basic learning tasks like Y-maze or Morris water maze, but a specific impact on anxiety and fear learning when neuronal IL-4Rα is absent in the CNS." (PMID 35587822, 2022).
autoimmune disease (4 papers, 2012 to 2025). A disorder resulting from loss of function or tissue destruction of an organ or multiple organs, arising from humoral or cellular immune responses of the individual to their own tissue constituents. "NETs were previously shown to be the major inducer of type I IFN production by plasmacytoid DCs during autoimmune disease, a possible explanation for NETs’ downregulation of the IL-4R would be through the production of IFN by NETs-treated monocytes." (PMID 28567039, 2017).
bladder cancer (4 papers, 1996 to 2025). "IL-4Rα is highly expressed in human bladder cancer tissues, and its overexpression is associated with a more advanced grade and stage." (PMID 41154660, 2025). "Our IHC and RT-PCR results for IL-4R expression were largely confirmed by RNAseq data from 230 human bladder cancer specimens deposited at The Cancer Genome Atlas (TCGA) database." (PMID 25208941, 2014). "When gene expression data for IL-4Rα were compared between the grade of bladder cancer, the TCGA data analyses showed that lower stage disease has higher gene expression compared to high-grade specimens (P < 0.03) and fold difference of 1.35." (PMID 25208941, 2014). "IL-4Rα is overexpressed in five bladder cancer cell lines, while normal bladder and human umbilical vein cell lines (HUVEC) expressed at low levels." (PMID 25208941, 2014). "We used Cochran–Armitage Statistics with exact two-sided P-values to examine the trend analysis of IL-4Rα over grade or stage of the bladder cancer specimens." (PMID 25208941, 2014). "IL-4Rα expression was examined in human bladder cancer cell lines, mouse xenografts, and biopsy specimens at mRNA and protein levels by real-time RT-PCR and IHC/ISH techniques." (PMID 25208941, 2014). "While these databases provide data from various tumors, none of these databases have published gene expression data from bladder cancer or IL-4Rα expression." (PMID 25208941, 2014). "TCGA data analyses showed that IL-4Rα gene was expressed in bladder cancer samples." (PMID 25208941, 2014). "However, RNAseq revealed a 1.35-fold difference for IL-4Rα expression in low-grade bladder cancer specimens compared to high-grade specimens (P ≤ 0.03)." (PMID 25208941, 2014). "Based on these results, we identify that human bladder cancer express type II IL-4R." (PMID 25208941, 2014). "Bladder cancer xenografts in immunodeficient mice also maintained IL-4Rα overexpression in vivo." (PMID 25208941, 2014). "Expression of IL-4Rα in bladder cancer appeared to correlate with advanced grade of disease." (PMID 25208941, 2014). "Five human bladder cancer, one normal bladder, and one HUVEC endothelial control cell lines were studied for expression of the three subunits of IL-4R at mRNA and protein levels." (PMID 25208941, 2014). "It is also not known whether human bladder cancer expresses IL-4R and which receptor chains are present in these cells." (PMID 25208941, 2014). "The significance of IL-4R expression in human cancer and in bladder cancer is not clear." (PMID 25208941, 2014).
chronic obstructive pulmonary disease (4 papers, 2014 to 2025). A chronic and progressive lung disorder characterized by the loss of elasticity of the bronchial tree and the air sacs, destruction of the air sacs wall, thickening of the bronchial wall, and mucous accumulation in the bronchial tree. "This response was completely blocked by anti-IL-4Rα treatment at both mRNA and protein levels, an observation in line with our previous findings in BECs from chronic obstructive pulmonary disease (COPD) patients." (PMID 40370530, 2025). "In the latest clinical guidelines, dupilumab—a monoclonal antibody targeting the interleukin-4 receptor alpha (IL-4Rα)—has been approved as an anti-inflammatory treatment for a select subgroup of patients with eosinophilic chronic obstructive pulmonary disease (COPD)." (PMID 40771814, 2025). "Associations among PAR-2, interleukin-4 receptor (IL-4R), transforming growth factor (TGF)-β and thymic stromal lymphoprotein (TSLP) have already been investigated in bronchial asthma, chronic obstructive pulmonary disease (COPD) and idiopathic lung fibrosis." (PMID 25009615, 2014). "Interestingly, STUB1 mRNA levels are up-regulated in the airways of subjects with asthmatic and chronic obstructive pulmonary disease (COPD), suggesting that elevation of STUB1 expression may serve as a possible feedback mechanism in an effort to dampen IL-4Rα signaling." (PMID 28721208, 2017).
Cognitive impairment (4 papers, 2018 to 2025). Abnormal cognition is characterized by deficits in thinking, reasoning, or remembering. "Interestingly, IL-4 plays an important role in cognition, since its impairment, caused by a lack of T cells that produce it or by the abolishment of IL-4R, is associated with cognitive impairment in learning tasks on the Morris water maze (MWM)." (PMID 39595890, 2024).
fibrosis (4 papers, 2014 to 2023). the formation of excess fibrous connective tissue in an organ or tissue in a reparative or reactive process. "The subsets of monocytes from individuals with different degrees of periportal fibrosis were evaluated regarding the expression of the profibrotic markers such as IL-4Rα and TGF-β and proinflammatory cytokines such as IL-6 and TNF-α." (PMID 24757288, 2014). "Thus, IL-4Rα-elicited type 2 immune effector responses like granuloma formation and fibrosis are important for the host survival during acute schistosomiasis." (PMID 28827803, 2017).
lymph node metastasis (4 papers, 2019 to 2022). "Correspondingly, others have shown that high IL-4Rα protein expression in CRC was associated with lower incidence of lymph node metastasis." (PMID 32512917, 2020). "Age of patients, serum level of CA19-9, tumor stage, T category, lymph node metastasis, distant metastasis, histologic type, histologic grade, Nu-IL4Rα, Cy-IL4Rα, Nu-IL13Rα1, and Cy-IL13Rα1 were included in multivariate analysis." (PMID 35207737, 2022). "The factors significantly associated with both cancer-specific survival (CSS) and relapse-free survival (RFS) in univariate survival analysis, were sex, age of patients, tumor size, tumor stage, lymph node metastasis, and immunohistochemical expressions of IL4Rα and IL13Rα1." (PMID 31540495, 2019).
malignant glioma (4 papers, 2002 to 2019). A grade III or grade IV glioma arising from the central nervous system. "Human malignant glioma cell lines and malignant astrocytic tumor specimens derived from surgical samples have been shown to overexpress high-affinity IL-4 receptors (IL-4R) in vitro and in situ." (PMID 22069569, 2010). "The absence of γc protein indicated that medulloblastoma cell lines express type II IL-4R as do malignant glioma cells." (PMID 11870521, 2002). "The significance of IL-4R expression on malignant glioma cells is still unclear." (PMID 22069569, 2010).
periodontitis (4 papers, 2017 to 2024). An acute or chronic inflammatory process that affects the tissues that surround and support the teeth. "A positive association was found between the IL-4R Q551R polymorphism and occurrence of chronic periodontitis in a meta-analysis." (PMID 35454140, 2022). "In the present study, we systematically searched and evaluated case-control studies addressing the association between IL-4 and IL-4R polymorphisms and periodontitis susceptibility." (PMID 28392616, 2017). "The SNP -Q551R of IL-4R (rs1801275) and susceptibility to periodontitis have also been discussed." (PMID 28392616, 2017). "Our study showed that the IL-4R Q551R R allele could significantly increase susceptibility to periodontitis in Caucasians, especially in terms of CP, which was more evident in those having a history of tobacco smoking." (PMID 28392616, 2017). "In addition, two more polymorphisms, that is, the IL-4-1099T/G and IL-4R Q551R, are discussed in our study, and it is revealed that the IL-4R Q551R allele may increase the susceptibility to periodontitis in Caucasians." (PMID 28392616, 2017). "In the present study, we performed meta-analyses concerning the relationship between susceptibility and periodontitis (including CP and AgP) and polymorphisms including the IL-4 -590C/T, -33C/T, -1099T/G, 70-bp VNTR, and IL-4R Q551R, in the overall population and specific subgroups." (PMID 28392616, 2017).
prostate carcinoma (4 papers, 2022 to 2025). A carcinoma that arises from epithelial cells of the prostate gland. "IL4R mutations were found to be associated with shorter survival in colorectal and prostate cancers (3 studies)." (PMID 35444210, 2022). "Furthermore, a generalized linear mixed model identified statistically significant associations between prostate cancer risk and SNPs in IL12RB2, IL13, IL17A, IL4R, MAPT, and TFNRS1B." (PMID 37108754, 2023). "In an animal model of prostate cancer, drug inhibition of IL4Rα did not affect tumor growth." (PMID 39758935, 2025).
renal fibrosis (4 papers, 2021 to 2025). A final common manifestation of a wide variety of chronic kidney diseases characterized by glomerulosclerosis and tubulointerstitial fibrosis. "Our study has demonstrated that IL-4 receptor α (IL-4Rα)/STAT6 axis play an important role in renal fibrosis." (PMID 36159833, 2022). "Loss of IL-4Rα inhibits STAT6 activation, suppresses bone marrow-derived fibroblasts activation, impairs macrophage M2 polarization, and attenuates renal fibrosis." (PMID 36159833, 2022). "Moreover, IL-4Rα deficiency results in inhibition of bone marrow-derived fibroblast activation and markedly reduces the progression of renal fibrosis, highlighting the potential therapeutic implications of targeting IL-4Rα in fibrotic kidney diseases." (PMID 40521043, 2025). "Recent data reveal that IL-4Rα/STAT6 signaling pathway drives bone marrow-derived fibroblasts and pro-fibrotic M2 macrophages accumulation in renal fibrosis." (PMID 36159833, 2022). "We have previously demonstrated that inhibition of IL-4Rα/STAT6 signaling impairs macrophages M2 polarization and attenuates renal fibrosis." (PMID 36159833, 2022). "We have showed that the IL4Rα/JAK3/STAT6 signaling pathway play an important role in the activation of myeloid fibroblast and the development of renal fibrosis." (PMID 34512669, 2021). "More recently, we have reported that knockout of IL-4Rα inhibits STAT6 activation and suppresses M2 macrophage polarization and renal fibrosis." (PMID 34831280, 2021). "Furthermore, we have shown that knockout of IL-4Rα inhibits STAT6 activation, myeloid fibroblast accumulation and transformation into myofibroblasts, M2 macrophage polarization, and development of renal fibrosis following obstructive injury or folic acid administration." (PMID 34512669, 2021).
acne (3 papers, 2021 to 2024). An inflammatory process of the sebaceous glands which is characterized by comedones, nodules, papules and/or pustules on the skin. "Thus it is hypothesized that IL-4 and IL-4R are involved in the inflammatory processes associated with acne." (PMID 33849530, 2021). "While the specific roles of IL-4 and IL-4R in the pathogenesis of acne are unclear, these proteins are known to play a role in inflammatory responses." (PMID 33849530, 2021). "Furthermore, a study in Saudi Arabia found that the IL4R Q551R SNP was significantly associated with acne but not acne severity." (PMID 33849530, 2021).
Arthritis (3 papers, 2005 to 2019). Inflammation of a joint. "Interestingly, in proteoglycan-induced arthritis, mice deficient in IL-4Rα showed higher IL-1β, IL-6 and MIP1a, whereas levels of IFNγ and autoantibodies were less affected." (PMID 23092393, 2012). "Previous studies have linked IL-4 signaling through IL4Rα to activation of STAT6 pathways and protection in inflammatory models of arthritis." (PMID 30849228, 2019). "The upregulated expression of TNF-α, IL-1α, IL-1β, IL-4R, P-selectin, MIP-1α (CCL3), MCP-1 (CCL2), NOS2 and NOS3 demonstrated in the present study is in agreement with previous observations of the dependency of the rat SCW-induced arthritis model on these mediators." (PMID 15642130, 2005).
hepatocellular carcinoma (3 papers, 2019 to 2022). A malignant tumor that arises from hepatocytes. "For instance, Circ-0038718 consists of exons 2 and 3 derived from the gene encoding the Interleukin-4 Receptor (IL4R) and is highly overexpressed in hepatocellular carcinoma." (PMID 35269391, 2022). "Furthermore, IL4R plays an essential role in regulating hepatocellular carcinoma (HCC) cell survival, proliferation, and metastasis and regulates the activation of JAK1/STAT6 and Jnk/Erk1/2 pathways." (PMID 31540495, 2019).
Hodgkins lymphoma (3 papers, 2021 to 2024). A heterogeneous group of malignant lymphoid neoplasms of B-cell origin characterized histologically by the presence of Hodgkin and Reed-Sternberg (HRS) cells in the vast majority of cases. "It should be noted that IL4R mutations have been observed in Hodgkin lymphoma previously, but were not discussed in the context of STAT6 activation." (PMID 37910143, 2023). "In addition, IL-4-binding fusion protein APG598 and IL-4R antagonist APG201 (R121D/Y124D) improved the chemosensitivity of Hodgkin lymphoma cells, which indicates that the combination of classical chemotherapy with IL-4/IL-13 antagonists may improve the efficacy of the both in cancer treatments." (PMID 33804263, 2021).
inflammatory bowel disease (3 papers, 2013 to 2024). A spectrum of small and large bowel inflammatory diseases of unknown etiology. "SNPs in interleukin IL-12β is associated with susceptibility to inflammatory bowel diseases, and SNPs in anti-inflammatory IL-4/IL-4R is associated with susceptibility to type I diabetes mellitus." (PMID 36553455, 2022). "Of these, immune trait-associated variants were found near TNCR18, associated with inflammatory bowel disease (IBD) and ankylosing spondylitis (AS), IL4R associated with psoriasis (PSO) and asthma and TNCR1 associated with PSO." (PMID 38549844, 2024).
lymphoma (3 papers, 2015 to 2022). A malignant (clonal) proliferation of B- lymphocytes or T- lymphocytes which involves the lymph nodes, bone marrow and/or extranodal sites. "Most strikingly, the combination of removal of apoptotic lymphoma cells from the graft inoculum together with IL-4Rα deficiency led to the most marked inhibitory effect on tumor growth and also to a significant reduction in TAM accumulation." (PMID 25702581, 2015). "Moreover, genes encoding CD74 and IL4R are expressed in lymphoma biopsies isolated from all stages of disease." (PMID 36353222, 2022). "Here, we investigated the ability of anti-CD20/anti-CD74 and anti-CD20/anti-IL4R bispecific antibodies to bind their designated targets on lymphoma cells and to kill their targeted cells via different mechanisms." (PMID 36353222, 2022). "Next, we determined MS4A1 (CD20), CD74 and IL4R gene expression levels in 84 lymphoma samples across different tumor stages (stage I-III/IV) and compared to expression in 12 healthy tissue controls using quantitative PCR of tissue biopsies." (PMID 36353222, 2022). "Our investigations into the IL-4/IL-13 axis indicated that global expression of IL-4Rα was required for optimal pro-tumor effects of apoptotic lymphoma cells, as well as optimal TAM accumulation." (PMID 25702581, 2015). "The use of a starry-sky lymphoma model in immunocompetent, wild-type (WT) mice additionally provided the opportunity to study the role of IL-4Rα, since several of the genes upregulated in SS-TAMs were IL-4Rα dependent (asterisks)." (PMID 25702581, 2015). "Both compounds inhibited the IL-4 pathway by acting on IL-4Rα, JAK3, and STAT6 activation in lymphoma cells (DND39) and fibroblasts (NIH3T3)." (PMID 36364420, 2022). "Notably, none of the modulatory effects induced by apoptotic lymphoma cells required macrophage IL-4Rα, indicating that the tumor-promoting effects of apoptotic λ-MYC cells and global IL-4Rα may be independent." (PMID 25702581, 2015).